TNF (tumor necrosis factor)
Diseases named in the same sentence as TNF in open-access papers (continued):
Sharing a sentence is not in itself a finding about the gene and the disease.
tuberculosis (continued). "The key cytokines and chemokines that play a role in the comorbidity of COPD and tuberculosis are interleukins 1β, 6, and 8 (IL-1β, IL-6, IL-8), TNF-α, and interferon gamma (IFN-γ)." (PMID 40141021, 2025). "TNF-α inhibitors increase the risk of developing tuberculosis (TB)." (PMID 40508064, 2025). "Tuberculosis triggers a robust immune response that involves the release of key pro-inflammatory cytokines, including tumor necrosis factor-alpha, interleukin-1, interleukin-6 (IL-6), interferon-gamma (IFN-γ), and interleukin-12 (IL-12)." (PMID 39941433, 2025). "A nationwide population-based study in South Korea found that among IBD patients treated with anti-TNF-α therapy, the incidence rates of tuberculosis were significantly higher than that among all IBD patients." (PMID 40763141, 2025). "Thirty-four of the 35 (97%) centres attained the recommendation of performing a chest radiograph to screen for tuberculosis prior to commencing anti-TNF therapy." (PMID 40065511, 2025). "It was obviously observed that tuberculosis has a high level of signal intensity in the five TNF-α inhibitors." (PMID 40371340, 2025). "In tuberculosis research, tumor necrosis factor (TNF)was shown to activate the same mitochondrial ROS (mROS) pathway in both human and zebrafish macrophages, leading to ROS production via reverse electron transport." (PMID 41108536, 2025). "Conversely, TB, caused by M. tuberculosis, elicits a strong immune response marked by the activation of immune cells and increased production of pro-inflammatory cytokines such as TNF-α, IL-1β, and IL-6." (PMID 40917351, 2025). "However, TNF-α inhibitors are associated with aggressive infections, such as candidiasis and tuberculosis (TB)." (PMID 40949078, 2025). "In our study, all patients who developed active tuberculosis were under TNF-inhibitors particularly Adalimumab and Infliximab." (PMID 40557175, 2025). "Among the cells involved, macrophages, neutrophils, and dendritic cells are activated and release proinflammatory cytokines, such as TNF-alpha and IL-8, which maintain tissue damage and remodeling, even after complete treatment of tuberculosis." (PMID 41598199, 2025). "This study suggests that patients undergoing biotherapy, particularly TNF-inhibitors have a higher incidence of active tuberculosis compared to the general population." (PMID 40557175, 2025). "Understanding the pleiotropic functions of TNF in tuberculosis pathogenesis is crucial for developing safe immunomodulatory strategies and optimizing the clinical management of patients at risk of latent TB reactivation." (PMID 40427602, 2025). "As is currently done in the care of patients with tuberculosis, we suggest increased considerations and caution be taken when prescribing or maintaining T. gondii seropositive patients on anti-TNF-α therapy." (PMID 39959486, 2025). "Careful pre-biologic screening for tuberculosis and other infections is essential before initiating TNF-α inhibitors." (PMID 41409967, 2025). "We advise T. gondii seropositivity testing be considered before and after initiation of anti-TNF-α therapy as is done for other infections such as tuberculosis." (PMID 39959486, 2025). "Although IL-17 has been shown to play a role in neutrophil mobilization and mucosal immunity, it has also been found to be less effective than TNF in tuberculosis-specific defense responses such as granuloma formation." (PMID 40806803, 2025). "Multiple regression analyses showed a significant association between the levels of TNF, TNFR1, TNFR2, tuberculosis status, and the AA homozygosity on the rs11684747 SNP." (PMID 38881671, 2024). "Excessive or dysregulated production of TNF-α can also contribute to immunopathology in tuberculosis." (PMID 38892443, 2024). "Management of TBI is a core intervention to achieve tuberculosis elimination, with patients treated with TNF-a inhibitors and other biologics representing a vulnerable group deserving specific attention." (PMID 39356910, 2024).
tuberculosis (continued). "Previous studies have revealed that, IL-6 and TNF play crucial role in the immune response to tuberculosis." (PMID 39015338, 2024). "The panel we employed included cytokines that are elevated in tuberculosis, i.e., interferon gamma (IFNγ), IL-2, IL-5, IL-10, IL-17, GM-CSF and TNFα." (PMID 38415011, 2024). "The results demonstrated the significant role of TNF-α in tuberculosis, playing a crucial role in an effective host immune response." (PMID 39101140, 2024). "Both of these processes overlap at the systemic (the general symptoms of tuberculosis and thyrotoxicosis are similar) as well as local level, i.e., in the thyroid gland itself as atrophic inflammation (TNF alpha, IL-1, IL-6) with apoptosis and destruction." (PMID 39767631, 2024). "Studies of miR-708 in both macrophage-like and non-immune cell lines identified the roles of this miR in the regulation of tumor necrosis factor alpha/interleukin 1 beta, arachidonic acid pathways and inflammatory responses to mycobacterium tuberculosis." (PMID 38556087, 2024). "Patients with active tuberculosis have been shown to have a higher proportion of central IFN-γ+TNF-α+ CD4+ T cells and a lower proportion of CD8+ effector T lymphocytes." (PMID 39065554, 2024). "Patients receiving TNF inhibitors have reported increased rates of upper respiratory tract infections, pharyngitis, sinusitis, and rhinitis; moreover, cases of tuberculosis have emerged during clinical trials of TNF inhibitors." (PMID 38392619, 2024). "KEGG enrichment analysis revealed that differentially expressed genes were mainly concentrated in the signaling pathways of cytokine-cytokine receptor interaction, PI3K-Akt, tuberculosis, NF-kB, TNF, MAPK, etc.." (PMID 38287405, 2024). "These primarily included anti-thyroid drugs, tumor necrosis factor inhibitors, anti-tuberculosis drugs, psychoactive agents, and others." (PMID 38562462, 2024). "Oral supplementation of A. muciniphila MucT in mouse models of tuberculosis reduces infection, lessens pathology, and reduces circulating TNF." (PMID 39305271, 2024). "Recent evidence suggests that IL-6, IL-8, and TNF-α are not only protective in tuberculosis but that the picture is more complex." (PMID 38933114, 2024). "In an anti-tuberculosis drug-induced liver injury rat model, pyrrolidine dithiocarbamate effectively decreased the serum level of cytokines (TNF-α, IL-1β, and IL-6) by repressing the phosphorylation of JAK2 and STAT3." (PMID 38543164, 2024). "This study aims to evaluate the diagnostic accuracy of a Mycobacterium tuberculosis (MTB)-specific triple-color FluoroSpot assay (IFN-γ/IL-2/TNF-α) in the differentiation of tuberculosis (TB) infection status in febrile patients." (PMID 39845975, 2024). "Treatment optimization through dose escalation was applied in 5.9% of cases, while anti-TNFα therapy was discontinued in 7.6% of patients due to complications such as tuberculosis reactivation, thymoma, or death." (PMID 39677079, 2024). "While TNFα serum levels were similar between the three groups, patients with active tuberculosis showed higher systemic SAA levels as compared to both healthy and LTBI controls." (PMID 37153579, 2023). "And, TNF-α levels were normal in 21 (84%) control subjects as compared to tuberculosis (TB) patients." (PMID 37007342, 2023). "Therapy with TNF-α inhibitors can result in the reactivation of latent infections, such as tuberculosis or the hepatitis B virus." (PMID 37568441, 2023). "tuberculosis coinfections in Indian adults are associated with lower circulating levels of inflammatory cytokines, including IFN-γ, TNF-α, IL-17A, and IL-17F alongside increased type 2 cytokines IL-4, IL-5, and IL-13." (PMID 39816832, 2023). "This increased TB risk may arise due to its impact on cell-mediated immunity; anti-TNF agents could reduce the number of CD8+ cells responsible for countering Mycobacterium tuberculosis." (PMID 37842480, 2023).
tuberculosis (continued). "One of the best-known examples is represented by the tuberculosis (TB) risk with anti-TNF agents, having been identified only after approval of this inhibitor by the regulatory authorities and the subsequent recommendations for an appropriate screening and preventive therapy." (PMID 37443755, 2023). "The KEGG term suggested that DEGs participate in the tuberculosis process via the NF- κB, TNF, T cell receptor, toll-like receptor, C-type lectin receptor signaling pathways, and so on." (PMID 36845395, 2023). "Stimulation of Mtb-HSP PBMCs resulted in an increase in the level of pro-inflammatory cytokines, TNF-α and IL-6, in the sera of patients with SA and tuberculosis compared to those of healthy controls." (PMID 36982159, 2023). "In these patients where TNF-alpha is contraindicated, it is also important to consider the type of contraindication that patients have to TNF-alpha (e.g., active tuberculosis is also a contraindication for brodalumab)." (PMID 37240650, 2023). "Protective immunity against tuberculosis (TB) requires a Th-1 response with cytokines like TNF and IFN-γ which plays a key role in the recruitment and activation of immune cells." (PMID 36662839, 2023). "The KEGG terms were mainly involved in the regulation of the actin cytoskeleton, tuberculosis, and the tumor necrosis factor (TNF) signaling pathway." (PMID 38203692, 2023). "TNF-α inhibitors can increase bacterial and mycobacterial infections in patients as well as reactivate latent infections, including hepatitis B and tuberculosis, with its immunosuppressive activity." (PMID 35223745, 2022). "A systematic review and meta-analysis of published trials found a higher incidence rate of any infection (20%), serious infection (40%), and tuberculosis (250%) related to anti-TNF therapy." (PMID 35223745, 2022). "Thus, special caution must be taken when administering TNF inhibitors to elderly individuals and individuals living in, or from areas of endemic tuberculosis (TB) disease or other pathogens that cause pneumonia." (PMID 36159650, 2022). "Tuberculosis is the main cause of death in silicosis, and many studies have found that cytokines (IFN-γ, IL-1β and TNF-α) that can inhibit the immune escape of tuberculosis are decreased, but some Th2 cytokines are increased in silicosis." (PMID 36587204, 2022). "The KEGG analysis revealed that DEGs were mainly enriched in TNF signaling pathway, Tuberculosis, and Toll-like receptor signaling pathway." (PMID 35365066, 2022). "This implies that the risk of tuberculosis reactivation is rare with tocilizumab and that it is relatively safer than TNF inhibitors in terms of tuberculosis." (PMID 36430392, 2022). "Screening tests for latent tuberculosis by chest radiographic imaging and interferon gamma release assays for tuberculosis/PPD skin tests are mandatory before initiating TNF inhibitors in intermediate to high-burden areas for tuberculosis." (PMID 36430392, 2022). "The large-scale studies on the relationship between anti-TNF and infection focused predominantly on tuberculosis activation and opportunistic infections." (PMID 37274971, 2022). "In AC treated SjSS BMDMs, pathways involving host defense were upregulated, involving pathways for tuberculosis, viral, and influenza A. IFNβ, IFNγ, and TNF pathways were all elevated, indicating overactivated inflammatory cytokine signaling." (PMID 35597820, 2022). "In a meta-analysis, significant increases were found in anti-TNF drug use by 20% for any infection, 40% for severe infection, and 250% for tuberculosis reactivation." (PMID 37274971, 2022). "The success of the host anti-tuberculosis response depends on tight control of the expression of pro-inflammatory cytokines such as TNFα and IL1β." (PMID 36120339, 2022). "When the first TNF blocker (infliximab) was released for prescription around the turn of the Millennium, an increased occurrence of tuberculosis reactivation soon became apparent during ongoing treatment." (PMID 36036323, 2022).
tuberculosis (continued). "The underlying mechanism was suggested to be that the TNF inhibitor (infliximab) depletes specific immune cells (CD45RA+ effector memory CD8+ T cells), which are critical for the clearance of tuberculosis-infected macrophages." (PMID 36430392, 2022). "TNF-a and IL-6 levels in serum or peripheral blood mononuclear cells (PBMCs) were shown to be significantly higher in active tuberculosis compared to healthy controls." (PMID 35457250, 2022). "In case of the before matching cohort, the lack of significance is thought to be due to the relatively less rigorous tuberculosis screening in the early study period, when more patients were enrolled in the nbDMARD cohort than TNF inhibitor cohort." (PMID 35945635, 2022). "Upon discovery of cases of tuberculosis coinciding with the market launch of the TNF blockers, screening for LTBI was mostly carried out in the approval and dose-finding studies around the T‐cell co-stimulation inhibitor abatacept." (PMID 36036323, 2022). "The IFN-γ/TNF-α dual release fluorescence point test is a simple and effective way to diagnose active tuberculosis." (PMID 35463642, 2022). "The possibility of tuberculosis acquisition or reactivation is an important matter of concern with biologic therapies, especially with TNF-alpha inhibitors." (PMID 35741329, 2022). "KEGG pathway analysis suggested that these genes were markedly concentrated in the IL-17 signaling pathway, TNF signaling pathway, tuberculosis, and NOD-like receptor signaling pathway." (PMID 35413978, 2022). "TNF-signaling, Measles, Tuberculosis, C-type leptin receptor signaling and osteoclast differentiation were among the topmost enriched pathways." (PMID 35250546, 2022). "Blocking TNF-α with infliximab lead to increase of serious viral and bacterial infections and less commonly to fungal infections or tuberculosis." (PMID 36619513, 2022). "La reactivación de la infección latente de tuberculosis es un problema grave en estos pacientes, especialmente después de recibir terapia anti-TNF." (PMID 34559494, 2021). "Treatment of Mtb-infected macrophages with the prolyl-hydroxylase inhibitor Molidustat reduced the release of TNFα and IL-10, two key cytokines involved in the immune response in tuberculosis." (PMID 34149713, 2021). "In general, Vγ9Vδ2 T cells produce cytokines such as interferon-γ, tumor necrosis factor-α, and IL-17 to enhance the protection against tuberculosis." (PMID 34975844, 2021). "Reactivation of tuberculosis and fungal infections have emerged as significant infective complications of anti-TNF-α therapy." (PMID 34401295, 2021). "Concerning opportunistic intracellular bacterial infections, tuberculosis (TB) is one of the most studied, since TNFα is responsible for the recruitment and effector function of neutrophils and lymphocytes to battle the infection." (PMID 33540543, 2021). "The tuberculosis prevalence rate was consistently higher for all anti-TNF drugs than in the general population, with infliximab and adalimumab showing higher rates compared to etanercept." (PMID 34790122, 2021). "We selected TNFα and IL-10 because both are key mediators for orchestrating the immune response in human tuberculosis." (PMID 34149713, 2021). "Demographic features, TNF-a antagonist type/treatment time, tuberculosis skin test (TST) and QuantiFERON results, isoniazid prophylaxis status, and concomitant corticosteroid (CS) treatments were collected." (PMID 33535732, 2021). "Strict adherence to guidelines for prescribing TNF-α blockers led to a decrease in tuberculosis’s incidence rate ratios to that of the normal-population." (PMID 34790122, 2021). "Tuberculosis induces pulmonary fibrosis via macrophage apoptosis, recruiting TNF-α, TGF-β, Th1 and Th2 cytokines." (PMID 34393772, 2021). "In tuberculosis macrophage-derived TNFα and IL-10 play a special role and the balance between these mediators affect the outcome of tuberculosis infection." (PMID 34149713, 2021).
tuberculosis (continued). "The PBMC-based model has also been shown to capture latency and tuberculosis reactivation via TNF-α inhibition; however, they lack experimental control of aggregation." (PMID 34572395, 2021). "In tuberculosis, TNF-α has been shown to be critical, with low levels associated with fatal disease; however, excessive TNF-α induces a hyper-inflammatory environment." (PMID 34026898, 2021). "TNF constitutes a critical host defense against tuberculosis, although excessive of TNF induces necrosis via mitochondrial reactive oxygen species in macrophages during M. marinum infection." (PMID 33928042, 2021). "Detection and treatment of LTBI prior to anti-TNF therapy decrease the chance of active tuberculosis." (PMID 33575041, 2021). "Nodal analysis revealed that IL-17A again had the greatest nodal connectivity in ART-naive participants with HIV–tuberculosis co-infection, with IL-1β and TNFα in second and third place." (PMID 34386782, 2021). "While it is well known that Th1 immunity controls tuberculosis in mice through key cytokines IL-12, TNF-α and IL1-β, they are variably expressed after BCG vaccination in mice." (PMID 33365029, 2020). "In another study, IFN-γ, IL-4, IP-10, and TNF levels in plasma were able to discriminate tuberculosis patients from household contacts with high sensitivity." (PMID 32962082, 2020). "Reactivation of tuberculosis (TB) has also been widely reported in patients receiving biologic therapies, in particular anti-TNF-alpha agents." (PMID 32615992, 2020). "The pro-inflammatory cytokine TNF-α is a critical immune mediator in the protection against and pathology of tuberculosis." (PMID 33271900, 2020). "The best described tuberculosis endotypes are deficiencies in interleukin (IL)-12, interferon (IFN)-γ or tumor necrosis factor (TNF) pathways, which result in decreased intracellular killing of M. tuberculosis." (PMID 33117351, 2020). "Several of these infectious complications were predictable in the light of preclinical models and early clinical trials (i.e., tuberculosis and TNF inhibitors; meningococcus; and eculizumab)." (PMID 32974356, 2020). "The detailed molecular dissection of these TNF-responsive pathways offers a wide array of potential new druggable targets, which have already been applied and validated in the zebrafish tuberculosis model." (PMID 32582182, 2020). "Antibody-mediated macrophage activation increases TNF-α secretion, which plays a major role in macrophage recruitment to the infection site during the initial and long-term control of tuberculosis." (PMID 32344637, 2020). "In line with our data, the overexpression of Hsp70 significantly prevented TNF-α and IL-6 release and mRNA expression in rat macrophages and tuberculosis patient’s macrophages." (PMID 32899721, 2020). "For example, IFN-γ, TNF-α, and IL-10 expression is increased in Asian elephants seropositive for tuberculosis, and TNF-α and IFN-γ are upregulated in in vitro stimulated immune cells from elephants with EEHV." (PMID 32992555, 2020). "Consistent with the start of administration of TNF inhibitors, screening tests, including those for tuberculosis and hepatitis B, are required prior to the administration of high doses of corticosteroids." (PMID 32377946, 2020). "The present study for the first time showed that CCL2 has a positive correlation with IL-12 and Th1 cytokines such as IFN-γ and TNF-α and hence essential for proper Th1 response against tuberculosis." (PMID 33381602, 2020). "Using a human, in-vitro granuloma model, we reproduce the increased reactivation rate of tuberculosis following exposure to Adalimumab compared to Etanercept, two TNF-α-neutralizing biologics." (PMID 32069329, 2020). "Increased levels of serum TNF-α has been observed in several infectious diseases including brucellosis, advanced tuberculosis, acute-phase Mediterranean spotted fever and malaria." (PMID 31072917, 2019).